IFNG (interferon gamma)
Diseases named in the same sentence as IFNG in open-access papers (continued):
Sharing a sentence is not in itself a finding about the gene and the disease.
cancer (continued). "For instance, cancer cells of different origins express high levels of PD-L1 and IDO, either as a direct effect of cancer-related intracellular pathways or as a result of IFNγ stimulation by infiltrating immune cells." (PMID 29740793, 2018). "We showed that pro-inflammatory and anti-inflammatory cytokines IFNγ, TNFα, and IL-10 did not induce expression of B7x on human or murine cancer cells." (PMID 29137299, 2017). "Although pro‐inflammatory cytokines, such as TNFα, IFNγ, and IL‐6, are considered to be among the main drivers of cancer cachexia, none of the numerous therapeutic strategies that were developed to target these factors have shown any clear success." (PMID 28264935, 2017). "Indeed, we show that innate immune stimuli (oncolytic virus (VSVΔ51-GFP), interferon γ (IFNγ), and tumour necrosis factor-like weak inducer of apoptosis (TWEAK)) combine with SMCs in vitro to reduce cell viability in the Kym-1 RMS cancer cell line." (PMID 27966453, 2017). "While IFNγ blocks tumorigenesis in multiple scenarios, many other cytokines have context dependent positive and/or negative effects on cancer." (PMID 26030458, 2015). "The immFocus approach resulted in the same conclusion for IFNγ, but without the need to specifically test it in T cells purified from the cancer microenvironment." (PMID 26384298, 2015). "In GBM cells, ICAM-1 expression has been shown to increase following stimulation with proinflammatory cytokines, such as interleukin-1β (IL-1β), tumor necrosis factor-alpha (TNFα), and interferon-gamma (IFN-γ), indicating that ICAM-1 is one of the inflammatory mediators also in this type of cancer." (PMID 26798546, 2015). "In summary, immunological control of cancer cells with high COX-2 expression by antigen-specific T cells may be less effective because of increased local release of IL4 and IDO and blunted interferon-gamma secretion by antigen-activated cytotoxic T cells." (PMID 25501829, 2014). "In addition, TNF-α, interferon-gamma (IFN-γ), early growth response gene-1 (EGR-1), hypoxia-inducible factor 1 alpha (HIF-1α), and transforming growth factor-beta (TGF-β) upregulate flTF in cancer cells and endothelial cells." (PMID 25084809, 2014). "In cancer patients, inflammatory changes indicate that IDO may be induced by soluble factors including IFNγ, TNF-α, IL-1β, soluble CD40 ligand (sCD40L) and CTLA-4 ligation to CD80/CD86 expressed by DC." (PMID 24147117, 2013). "Interestingly, the sensitivity of model variables is robust against parameter variations and against differences between IFNγ induced STAT1 signalling in pancreatic stellate and cancer cells." (PMID 23284277, 2012). "Although IFNγ effects mediated by TNFRI would be inhibited by the presence of p21 in the cell cytoplasm, the p21 location in in situ carcinomas would be capable to inhibit the apoptotic pathway of TNFRI at ASK-1 level, and thus, to prevent the IFNγ function as cell cycle inhibitor." (PMID 17697357, 2007). "IL-12 reached amaximum in CIN II and decreased in CIN III and carcinoma; but the differencesbetween groups were statistically not significant (K. W. test: P=.068 for IL-12 + p40,P=.264 for IFNγ, P=.077 for TNFα and P=.071 for IL-2)." (PMID 18288269, 2007). "To investigate the role of IFNγ in PD-L1 upregulation, we first incubated cancer cells without or with CD64-CR T cells in the presence or absence of a scalar dose of the JAK2 inhibitor ruxolitinib, which inhibited the upregulation of PD-L1 in a dose-response manner." (PMID 39962623, 2025). "Thus, the interplay of factors like immune checkpoint types expressed in tumors, their baseline expression levels, and changes with and without IFNγ stimulation can complicate cancer therapy using immune checkpoint inhibitors such as antibody-based drugs." (PMID 40001596, 2025).
cancer (continued). "Moreover, IFNγ signaling is known to be key for effective checkpoint inhibition that is used in cancer immunotherapy to relieve immune cells of negative signals from check point proteins such as CTLA4 and PD1." (PMID 40586312, 2025). "In addition, IFNγ targets such as PTPN2, APLNR and the chromatin remodeling complex PBAF have been identified by genetic screens as putative enhancers of ICIs in preclinical cancer models." (PMID 39941003, 2025). "All the factors determining these paradoxical roles of IFNγ in cancer are not yet completely clear." (PMID 38684864, 2024). "Variations were observed in the proportion of monofunctional CD4 T cells producing TNF, particularly higher in individuals without cancer and patients treated with chemotherapy alone, while those treated with immunotherapy or chemoimmunotherapy predominantly produced IFNγ." (PMID 39257577, 2024). "Additionally, the binding of stress-induced ligands on the surface of cancer cells to the NKG2D receptor of NK and cytotoxic T cells prompt the secretion of immunomodulatory and pro-inflammatory cytokines, such as IFNγ, which further stimulate immunosurveillance." (PMID 38216787, 2024). "Reculstering of IFNγ pathway genes showed a shifted expression profile in the IFNγ pathway in sh61A CAL 27 cells, with pronounced downregulation of CD274 and CD47, reinforcing the conclusion that TRMT61A is critical to the reactive upregulation of PD-L1 on cancer cells during inflammation." (PMID 38730256, 2024). "In addition, the N803 induction of Th1 responses and IFNγ production in the absence of Treg expansion attribute this first-in-class heterodimeric IL-15 agonist with unique promise as a cancer therapeutic." (PMID 37371081, 2023). "Our findings revealed a positive correlation between the expression levels of LAG3 and IFNG (R = 0.76, p < 0.001), PRF1 (R = 0.75, p < 0.001), FASLG (R = 0.75, p < 0.001), GZMH (R = 0.74, p < 0.001), NKG7 (R = 0.74, p < 0.001), and PDCD1 (R = 0.73, P < 0 0.001) in pan-cancer tissues." (PMID 38115039, 2023). "Targeting the hypoxic conditions and HIF1α function in combination with anti-PD-L1 immunotherapy can overpass the adverse effect PD-L1, whether attributed to HIF1α or IFNγ in the TME, by enhancing the recognition of cancer cells and allowing effective cancer cell killing by the immune system." (PMID 37067635, 2023). "The transferred CAR-CD4+ T cells killed cancer cells via Perforin- and IFNγ-dependent mechanisms but could not eliminate IFNγ-resistant tumors." (PMID 37965314, 2023). "In addition, IFNγ expression is induced by radiation and ICB in cancer treatment." (PMID 37151134, 2023). "IDO could also catalyze tryptophan to kynurenine in cancer cells, decreasing the expression of NKG2D ligands on the surface of cancer cells by ADAM10, and this reduced expression of NKG2D ligands inhibited degranulation and IFNγ release by NK cells." (PMID 38022646, 2023). "Given the functional connection between STAT1 and type I PRMTs in modulating cancer persistence, we hypothesized that PRMTi could be effective in reducing persisters even without exogenous IFNγ stimulation." (PMID 35089788, 2022). "As shared features of cell anergy in cancers, NK cells have been reported have decreased levels of NKG2D (a major activator receptor), together with impaired degranulation capabilities and reduced production and release of cytolytic molecules, such as perforin, granzymes, and IFNγ." (PMID 36338516, 2022). "However, the role of IFNγ produced by Th17 cells and Th22 cells has not been specifically studied in this or other types of human cancer." (PMID 34385592, 2022). "Specifically, anti-PD-L1 antibodies stimulate CD8+ T cells to release cytokine IFNγ to activate the JAK-STAT1 pathway in cancer cells, thereby reducing the expressions of SLC7A11 and SLC3A2, and ultimately increasing the sensitivity of cancer cells to ferroptosis." (PMID 34796174, 2021).
cancer (continued). "First, IFNγ fails to induce the expression of PD-L1 protein in certain cancers." (PMID 33849634, 2021). "M1 macrophages, which are defined as classically activated macrophages, possessed strong anti-cancer properties, they are normally activated during acute inflammation by toll-like receptor (TLR) ligands or by cytokines released mostly by Th1 cells (e.g., IFNγ, TNFα)." (PMID 34445735, 2021). "Notably, even more vigorous IFNγ responses were generated against further PCa epitopes, namely STEAP1292–300, PSMA469–477, and especially PAP135–143 as well as the well-known cancer-testis antigen NY-ESO1157–65 expressed in numerous cancer types." (PMID 34006895, 2021). "M(IFNG/LPS) CM-treated cells might use glutamine as an energy source to bypass limited endogenous glucose levels or favor activation of the pentose phosphate pathway (PPP), as observed in cancer cells, to enable cellular survival under metabolic stress." (PMID 33971957, 2021). "Studies have confirmed that IFNG released by cytotoxic T cells downregulates the expression of glutamate transport systems (SLC3A2 and XCT), thereby promoting lipid peroxidation and iron drop in cancer cells, which explains the close relationship between immunity and ferroptosis." (PMID 34868262, 2021). "It was shown that activated CD8+ T cells secrete IFNγ during immunotherapy, which down-regulates the expression of SLC7A11 (as well as its regulatory partner SLC3A2) and subsequently inhibits cystine uptake in cancer cells, thereby augmenting lipid peroxidation and ferroptosis." (PMID 33891303, 2021). "Moreover, this metabolic responses seem to be mediated by secretion of pro-inflammatory cytokines from cancer cells and also from the immune system of the host, including tumor necrosis factor (TNF), interferon-gamma (IFN-γ), and several interleukins (IL-6, IL-1β)." (PMID 32230855, 2020). "Interestingly, EBVaGCs exhibit the strongest signature of IFNγ response across the different GC subtypes, further suggesting that the IFNγ response in these cancers is not effectively blocked by EBV5,10." (PMID 32901107, 2020). "Non-metastatic cancer cells can mobilize IFNγ-producing monocytes to the lungs." (PMID 32849639, 2020). "Moreover, IFNγ was able to maximally induce MHCI on cancer cells and did not permit an additive effect from combining RT and IFNγ treatment in vitro." (PMID 32355214, 2020). "IFNγ is a key cytokine secreted by immune cells that can induce increased expression of HLA-I and II, and of immunoproteasome genes PSMB8, − 9, and − 10 in cancer cells, which may improve neoantigen processing and presentation." (PMID 31735170, 2019). "Therefore, measuring NKA for IFNγ secretion (NKA-IFNγ) might be valuable for screening GC and estimating cancer stage." (PMID 29050291, 2017). "For example, several pro-inflammatory cytokines, including interferon gamma (IFN-γ), tumor necrosis factor alpha (TNF-α), transforming growth factor beta (TGF-β), and interleukin-10 (IL-10), have been shown to contribute to both the initiation and development of cancer." (PMID 29268703, 2017). "However, it has been reported that interferon-gamma signaling may induce MHC-II in almost all cell types, including those derived from cancer." (PMID 28817603, 2017). "Therefore, we focused on siRNA-mediated target mRNA cleavage and hypothesized that robust knockdown of PD-L1 mRNA, with or without IFNγ stimulation, would also suppress PD-L1 expression on cancer cell surfaces." (PMID 40001596, 2025). "However, although NMFs secreted arginine rescued cancer cells from apoptosis under arginine-deprived conditions, co-culture with NMFs alone failed to restore JAK-STAT signaling in cancer cells exposed to IFNγ, as indicated by persistently low pSTAT1 and PSMB9 protein levels." (PMID 41511309, 2025).
cancer (continued). "Moreover, the addition of citrulline could restore the levels of total and phosphorylated STAT1 and PSMB9 proteins in response to IFNγ in ASS1-expressing cancer cells grown in an arginine-depleted medium, confirming the essentiality of arginine for the cancer cell response to IFNγ." (PMID 41511309, 2025). "Interestingly, our network-based analysis recognized the interactions between IFNG and the effector PTPs activated by PD-1 and CTLA4 signaling as a potential hub through which the effects of ICI cancer treatment could lead to the observed differences between irMyositis and DM38." (PMID 40759686, 2025). "While both perforin and interferon gamma were necessary for the PC blockade-dependent control of intracranial tumor growth, NK cells isolated from intracranial tumors demonstrated only a limited cancer cell killing ability, and PC blockade did not alter the abundance of NK cells within tumors." (PMID 39551601, 2024). "Inflammatory stimuli such as oxidative stress and treatment with cytokines IFNγ, IL-1α, TNFα have also been found to alter the glycosylation pattern of MUC16 in pancreatic cancer cells, suggesting that MUC16 may play a key role in promoting inflammatory signaling in cancer." (PMID 38361923, 2024). "Thus, there has not been strong clinical evidence to support the use of IFNγ in cancer treatment." (PMID 37671945, 2023). "Moreover, although several studies have shown that brevilin A treatment results in activation of JNK and p38, and inactivation of Akt in cancer cells, our results showed that brevilin A did not affect LPS/IFNγ-induced activation of MAPKs and Akt in RAW264.7 cells." (PMID 35774606, 2022). "Interestingly, M1 coinjection with cancer cells also resulted in decreased T-reg cell populations in CD4+ cells, which may have been related to IFNg-based macrophage activation and downstream M1–T cell crosstalk through IFNg/IL-12 signaling." (PMID 34835178, 2021). "Importantly, innate immune stimuli (e.g. oncolytic virus (VSVΔ51-GFP), interferon γ (IFNγ), and tumour necrosis factor-like weak inducer of apoptosis (TWEAK)) synergize with LCL161 in vitro to promote TNFα signaling and reduce cell viability in Kym-1 RMS cancer cells." (PMID 27966453, 2017). "In early-stage tumors, keratin-expressing cancer cells recruit Tregs via MHC class II, fostering an inflammatory phenotype with limited IFNγ production and non-clonally expanded T cells." (PMID 40523956, 2025). "They found that chemokines recruiting effector T cells were mainly produced by immune cells, not cancer cells, in the TME of a mouse model with IFNγ signaling pathway defects." (PMID 38418707, 2024). "Given that SOCS1 is a non-redundant inhibitor of IFNγ signaling, SOCS1 expression in cancer cells would dampen PD-L1-mediated checkpoint inhibition." (PMID 38415248, 2024). "This research offers a thorough comprehension of a complex process by which IFNγ triggers a non-canonical signaling cascade that involves STAT3 and c-Myc, leading to the manifestation of a unique metabolic phenotype of cancer cells." (PMID 38791327, 2024). "Along similar lines, IFNγ signaling can also boost the expression of non-classical MHC class Ia genes, such as HLA-G, -E and -F, which are known to endow cancer cells with ability to evade CTL and NK cell responses." (PMID 37762241, 2023). "Besides, interferon gamma response and interferon alpha were enriched in the results of GSEA concentrating RPL23A indicating that RPL23A might have significant roles in immune-related pathways, besides, therapies target Myc could also enhance the immunotherapy in cancers." (PMID 35637966, 2022). "In contrast, IFNγ release by TCR1376 or TCR9383B2 and TCR9383B14 engineered T cells was not above background when cancer cells were co-cultured without prior peptide loading, indicating that the endogenous KRASG12V protein is not recognized." (PMID 33875134, 2021).
cancer (continued). "Of note, the HLA-ABC negative cell line OVCAR8 failed to elicit robust IFNγ release in TICS and prime CD8+ T cell activation (data not shown), highlighting the necessity of TCR-HLA engagement for cancer cell recognition." (PMID 32200422, 2020). "TNFα and IFNγ, the two most studied cytokines in that context, have been shown to enhance MUC16 shedding in some but not all cancer cell lines suggesting also a complex regulation of MUC16 expression that is dependent on the cellular context." (PMID 31039761, 2019). "Downregulated pathways were similar to those described in a pan-cancer analysis of differentially expressed pathways between cancers with and without WGD, which found Allograft rejection, Inflammatory response and Interferon gamma response to be downregulated in samples with WGD3." (PMID 39025846, 2024). "While individuals without cancer and patients with cancer treated with CT alone harbor monofunctional spike-specific CD4 T cell producing TNF, the majority of monofunctional CD4 T cells in patients treated with IT alone or in combination with CT produce IFNγ." (PMID 39257577, 2024). "This corrective action of cancer on SARS-CoV-2-related inflammation does not seem to be unidirectional as COV/CA patients display enhanced activation of HLA-DR+CD38+CD4+ T cells, and increased IFNγ expression in PBMCs." (PMID 37063865, 2023). "However, our results showed that, according to the present protocol, cancer induction with DMH and/or NFRFP consumption does not modify serum concentrations of IFNγ, IL-6, IL-10, IL-12p70, MCP-1, and TNF-α." (PMID 34444868, 2021). "Finally, when all malignancy types in the TCGA collection were analyzed for correlation of this IFNγ-induced metagene signature and NAMPT expression, many other cancers exhibited similar if not stronger positive correlations." (PMID 33976173, 2021). "Because these three ICPRGs have the potential to be novel actionable targets in cancer therapy, we further examined these individual genes by Box and Whisker plots of log2 FPKM expression levels in IFNγ positive and negative tumors of CRC, SKCM, BC, ESC, STC, and LUSC." (PMID 32265897, 2020). "Interestingly, PD-L1 expression was not high on cancer cell clusters in either the LLC-NT or LLC-sh21 groups, indicating that although LLC-sh21 cells induce PD-L1 expression in vitro after IFNγ treatment, this is not reflected in vivo." (PMID 31133614, 2019). "Our results therefore allow the conclusion that the differences in IFNγ induced nuclear accumulation of STAT1 are not restricted to the two originally used cell lines but reflect a general difference between pancreatic stellate and cancer cells." (PMID 23284277, 2012). "Moreover, treatment for 120 h with EpCAM-ReTARGTPRIFNαR149A inhibited the proliferative capacity of the cancer cell lines OvCAR3 and PC3M by ~91% without compromising the viability of the TPR-specific CD8pos T cells and increased their capacity for IFNγ secretion." (PMID 40243928, 2025). "In vitro coculture of control HPAF-II cancer cells with nonadherent human PBMCs significantly suppressed the CD3/CD28-induced proliferation of both CD8 and CD4 T cells, and also reduced levels of IFNγ and GMCSF, cytokines important in generating an active antitumor immune response." (PMID 36922934, 2022). "However, cancers develop various defects to impair IFN signaling pathways, indicating that IFNγ therapy may not be useful in all cases." (PMID 33671123, 2021). "Cancer cells are not thought to be sources of IFNγ, but MHC-I expression can be directly regulated by type I interferon (IFN-I) signaling and studies have indicated that host responses to IFN-I through the receptor IFNAR are essential to the anti-cancer CD8+ T cell response driven by radiotherapy." (PMID 32355214, 2020).